ADAMTS8 (ADAM metallopeptidase with thrombospondin type 1 motif 8)
Description:
Has anti-angiogenic properties.
Synonyms: ADAM-TS8; METH2; FLJ41712
Tractability: Antibody: UniProt places it where antibodies can reach, with medium confidence; UniProt predicts a signal peptide or a membrane-spanning region; its Gene Ontology location is reachable by antibodies, with medium confidence.
Gene: Protein-coding gene on chromosome 11 (130,404,923 to 130,428,609, reverse strand). Ensembl gene ENSG00000134917.
Subcellular location: Secreted, extracellular space, extracellular matrix
Pathways (Reactome):
Disease: Defective B3GALTL causes PpS
Extracellular matrix organization: Degradation of the extracellular matrix
Metabolism of proteins: O-glycosylation of TSR domain-containing proteins
Gene Ontology:
Molecular function: integrin binding; low-affinity phosphate transmembrane transporter activity; metalloendopeptidase activity; metallopeptidase activity; zinc ion binding
Biological process: extracellular matrix organization; negative regulation of cell population proliferation; proteolysis; transmembrane transport
Cellular component: extracellular matrix
Genetic constraint (gnomAD): Loss-of-function variants: 52 observed, 60.87 expected, observed/expected ratio (o/e) 0.85, 90% interval 0.68 to 1.08. The upper end of that interval is the gene's LOEUF score, 1.08, which puts it in group 4 of 6, group 1 being the genes least tolerant of losing a copy. Missense variants: 1,190 observed, 1,126.6 expected, observed/expected ratio (o/e) 1.06, 90% interval 1.01 to 1.11. Synonymous variants: 555 observed, 487.15 expected, observed/expected ratio (o/e) 1.14, 90% interval 1.06 to 1.22.
Homologues: Orthologues: chimpanzee ADAMTS8 (99% identical), macaque ADAMTS8 (99% identical), pig ADAMTS8 (90% identical), dog ADAMTS8 (87% identical), rat Adamts8 (82% identical), mouse Adamts8 (81% identical), rabbit ADAMTS8 (74% identical), guinea pig ADAMTS8 (62% identical), zebrafish adamts8a (53% identical), zebrafish ADAMTS8 (52% identical), tropical clawed frog adamts8 (25% identical). Paralogues in human: ADAMTS1 (48% identical), ADAMTS15 (46% identical), ADAMTS9 (41% identical), ADAMTS4 (40% identical), ADAMTS5 (39% identical), ADAMTS20 (39% identical), ADAMTS7 (33% identical), ADAMTS6 (31% identical), ADAMTS12 (31% identical), ADAMTS14 (31% identical), ADAMTS3 (31% identical), ADAMTS10 (30% identical), and 13 more.
Diseases named in the same sentence as ADAMTS8 in open-access papers:
ADAMTS8 is named in the same sentence as 63 diseases in open-access papers, as found by Europe PMC text mining. Sharing a sentence is not in itself a finding about the gene and the disease. The quoted sentences say what the papers report.
lung carcinoma (12 papers, 2004 to 2025). "ADAMTS8 was found to inhibit tumor progression in lung cancer, and low ADAMTS8 expression was reported to be an important factor associated with poor patient prognosis." (PMID 38410799, 2024). "In lung cancer, ADAMTS8 enhances survival, especially in patients with wild-type EGFR or low PD-L1 expression, by promoting anti-cancer NKT cells and reducing immunosuppressive T cells." (PMID 40650042, 2025). "ADAMTS8 is an unfavorable predictor of lung cancer patients, and it mediates invasion and metastasis when expressed at a low level." (PMID 36947712, 2023). "To further verify the impact of ADAMTS8 on the target therapies of EGFR-mutant lung cancer, we assessed the levels of ADAMTS8 in several LUAD cell lines with mutated EGFR based on the sensitivity of TKI treatment." (PMID 35743687, 2022). "To elucidate the possible mechanisms for ADAMTS8 dysregulation in lung cancer, we assessed several epigenetic regulatory mechanisms, such as DNA methylation, copy number variation (CNV) and miR-RNA interaction." (PMID 35743687, 2022). "To evaluate the role of ADAMTS8 in lung cancer proregression, we performed GSEA to predict the cancer behavior by comparing the transcriptomes of ADAMTS8 in lung cancer patients with higher and lower expression in the TCGA database." (PMID 35743687, 2022). "The GSEA using the TCGA cohort also suggested that ADAMTS8 was involved in poor survival in the Shedden lung cancer cohort." (PMID 35743687, 2022). "This study took advantage of RNA-seq and bioinformatics to verify the role that ADAMTS8 plays in lung cancer." (PMID 35743687, 2022). "When cross-analyzing ADAMTS8 based on the levels of GATA1 in survival time, lung cancer patients with low-level ADAMTS8 survived for a shorter period when compared with high-level based on low GATA1 but not LMO2 expression." (PMID 35743687, 2022). "The results indicated that lung cancer patients with higher ADAMTS8 levels among wild-type EGFR or low PD-L1 groups survive longer than those with lower levels do." (PMID 35743687, 2022). "Meanwhile, we found that ADAMTS8 was downregulated in a variety of cancers including bladder cancer, brain cancer and lung cancer." (PMID 28410204, 2017). "A dramatic reduction of ADAMTS8 expression in lung cancer was observed in 23 paired normal and lung cancer tissues." (PMID 24213506, 2012). "Furthermore, a recent study indicated that ADAMTS8 inhibits the progression of lung cancer by suppressing the key angiogenesis factor, VEGFA (vascular endothelial growth factor A)." (PMID 40650042, 2025). "Low ADAMTS8 expression may contribute to a shorter survival duration and be a promising target for lung cancer patients who are ineligible for TKI or ICI treatment." (PMID 35743687, 2022). "Our findings revealed ADAMTS8 as a potential prognostic marker in lung cancer." (PMID 35743687, 2022). "This might imply that lung cancer patients ineligible for treatment with ICIs or EGFR TKIs might benefit from ADAMTS8 treatment." (PMID 35743687, 2022). "Taking advantage of clinical specimens and NGS with the aid of bioinformatics, this study has pointed out that ADAMTS8 might be involved in lung cancer pathogenesis." (PMID 35743687, 2022). "Moreover, several lung cancer cell lines have been investigated, and the results showed lower levels of ADAMTS8 compared with normal bronchial epithelial cells (HBE 135)." (PMID 35743687, 2022). "In conclusion, ADAMTS8 plays a role in lung cancer carcinogenesis and immunity." (PMID 35743687, 2022). "The results suggested that ADAMTS8 expression was reduced in lung cancer." (PMID 35743687, 2022). "In addition, four different cohorts, including Landi, Okayama, Selamat, Su and Hou, also showed that ADAMTS8 was downregulated in tumor parts in lung cancer patients." (PMID 35743687, 2022).
lung carcinoma (continued). "As disintegrins and metalloproteinases with thrombospondin motifs (ADAMTS8) are downregulated in NSCLC cells (H460 and A549 cells), the overexpression of ADAMTS8 could inhibit proliferation and induce apoptosis of lung cancer cells." (PMID 36033435, 2022). "ADAMTS8 comes from integrins and metalloproteinases of the thrombospondin motif, and some studies show that ADAMTS8 is closely associated with vascular endothelial growth factor A (VEGFA), and some studies have found that ADAMTS8 expression in lung cancer is very low." (PMID 37409245, 2023). "In contrast, there was no survival benefit of ADAMTS8 based on low-level but not high-level LMO2 in lung cancer patients." (PMID 35743687, 2022). "Previous studies have reported that downregulated ADAMTS8 expression in lung cancer and breast cancer did not correlate with clinicopathological factors." (PMID 27493958, 2016). "However, high expression of ADAMTS8, CD36, DPYSL2, PLEKHH2, STX11, and TCF21 tends to lead to better prognosis, which coincides with the difference in expression of these HUB genes in normal samples and lung cancer samples." (PMID 37409245, 2023). "This study utilized the precious clinical specimens sequenced by NGS and Big Data analysis via bioinformatics to elucidate a possible candidate gene, ADAMTS8, and provide a potential strategy for patients who have not benefited from TKIs or ICIs in lung cancer treatment." (PMID 35743687, 2022). "In addition, in lung cancer patients with wild-type EGFR, lower levels of ADAMTS8 might be of a survival benefit compared with higher levels." (PMID 35743687, 2022). "Moreover, the expression of miR-98-5p did not affect the OS of lung cancer patients, suggesting that miR-98-5p is not the main regulatory mechanism of ADAMTS8." (PMID 35743687, 2022). "At the same time, the expression of ADAMTS8 was not different between high and low levels of CTLA4 in lung cancer patients, and the benefits of higher ADAMTS8 expression were present regardless of the levels of CTLA4." (PMID 35743687, 2022). "ADAMTS8, but not other members of the ADAMTS family, plays a role in mediating lung cancer." (PMID 35743687, 2022). "In lung cancer patients with low expression levels of PD-L1, who might not benefit from ICI therapy, they survived for shorter times when they possessed lower levels of ADAMTS8 compared to patients with higher levels." (PMID 35743687, 2022).
breast carcinoma (9 papers, 2006 to 2025). "Through published cancer-related datasets and clinical validation, we found that ADAMTS8 and DNMT3A expression negatively correlated in breast cancer, and both associated with patient prognosis." (PMID 40323963, 2025). "Methylation-specific PCR (MSP) experiments confirmed that DNMT3A mediates ADAMTS8 promoter methylation in breast cancer." (PMID 40323963, 2025). "Taken together, our findings suggest that DNMT3A activates the EGFR-MEK-ERK signaling pathway by silencing ADAMTS8 transcription through methylation, thereby promoting breast cancer development." (PMID 40323963, 2025). "Previous studies have shown that the ADAMTS8 expression is down-regulated in breast cancer, brain cancer, and non-small cell lung cancer." (PMID 33851708, 2021). "Downregulation of ADAMTS8 through epigenetic silencing has been detected in multiple tumors including brain cancer, breast cancer and non-small cell lung cancer." (PMID 28410204, 2017). "De novo methylation, involving DNMT3A, plays an important role in cancer development; however, it remains unclear whether DNMT3A regulates the progressive expression of breast cancer by regulating ADAMTS8." (PMID 40323963, 2025). "The GSEA suggested the role of ADAMTS8 in EMT in breast cancer." (PMID 35743687, 2022). "Based on the TCGA-BRCA dataset, we found that LOXL1, SDC1 and PXDNL were highly expressed in breast cancer while the expressions levels of FBLN1, FBLN5 and ADAMTS8 were lower than those in normal breast samples." (PMID 37056938, 2023). "In this study, BM genes with differential expression and prognostic correlation in breast cancer were selected as promising prognostic biomarkers for breast cancer, including FBLN1, FBLN5, ADAMTS8, LOXL1, SDC1 and PXDNL." (PMID 37056938, 2023). "Similarly, breast cancer patients with increased PXDNL (p=0.00011) and SDC1 (p<0.0001), and decreased FBLN1 (p=0.033) and ADAMTS8 (p=0.00017) expression levels tended to have shorter disease-specific survival (DSS) time." (PMID 37056938, 2023). "In addition, they showed that ADAMTS8, along with ADAMTS15, are novel predictors of survival in breast cancer patients." (PMID 24213506, 2012).
pulmonary arterial hypertension (7 papers, 2020 to 2025). Pulmonary arterial hypertension (PAH) is a group of diseases characterized by mean pulmonary artery pressure >20 mmHg and elevated pulmonary arterial resistance leading to right heart failure. "ADAMTS8 was found to affect the right ventricle through the development of pulmonary arterial hypertension, causing its hypertrophy and motion abnormalities." (PMID 37623681, 2023). "Nevertheless, our data can be used to design small molecule inhibitors for other pharmaceutical targets, for example ADAMTS4 and ADAMTS5 in osteoarthritis, ADAMTS7 in atherosclerosis, or ADAMTS8 in pulmonary arterial hypertension, which spare ADAMTS9." (PMID 40449594, 2025). "ADAMTS8 knockout mice demonstrated improved pulmonary hypertension and right ventricular dysfunction." (PMID 37623681, 2023). "Specific deletion of ADAMTS8 in PASMCs ameliorated hypoxia-induced pulmonary hypertension in mice and reduced PASMC proliferation with upregulation of AMP-activated protein kinase (AMPK)." (PMID 38071234, 2023). "In a previous study on the chronic hypoxia-induced pulmonary hypertension model, the ADAMTS8-specific knockout mice of cardiomyocytes had significantly less right ventricular fibrosis than control mice." (PMID 35224040, 2022). "ADAMTS8 promoted the development of pulmonary arterial hypertension (PH) and right ventricular failure and the proliferation of PASMCs, ECM remodeling, and endothelial dysfunction in an autocrine/paracrine manner." (PMID 35224040, 2022). "For example, ADAMTS8 expression was significantly enhanced in pulmonary arterial hypertension and linear morphoea, a connective tissue disease." (PMID 35224040, 2022). "It has been reported that mebendazole could suppress ADAMTS8 expression in the lung and right ventricle and ameliorates pulmonary hypertension." (PMID 35224040, 2022). "In the pulmonary hypertension rat model induced by the Sugen/hypoxia model, the levels of ADAMTS8 in the lung and RV were significantly elevated, and cardiomyocyte-specific ADAMTS8 knockout mice showed significantly less RV fibrosis than the control mice after chronic hypoxia." (PMID 35224040, 2022). "ADAMTS8, as a paracrine mediator, has been reported to play a crucial role in the interaction between pulmonary artery smooth muscle cells (PASMCs) and pulmonary artery endothelial cells (PAECs) in the development of pulmonary hypertension (PH)." (PMID 35224040, 2022). "Recently, ADAMTS8 expression was found to be increased in lungs of patients with pulmonary arterial hypertension (PAH)." (PMID 34687701, 2021). "ADAMTS-8 expression was increased in the lungs of patients with pulmonary arterial hypertension (PAH) and in mouse/rat models of PAH." (PMID 33352066, 2020).
lymph node metastasis (6 papers, 2016 to 2025). "In GC, the methylation status of ADAMTS8 inversely correlates with the protein expression and lower ADAMTS8 levels associate with a higher invasive depth and with the presence of lymph node metastasis." (PMID 32456248, 2020). "A significant association was found between ADAMTS8 methylation status and lymph node metastasis in primary gastric cancer." (PMID 27493958, 2016). "Similar to the results of our study, in gastric cancer, ADAMTS8 downregulation, often linked to DNA hypermethylation, correlates with increased invasion and metastasis, as its expression is inversely related to invasive depth and lymph node metastasis." (PMID 40650042, 2025). "A significant association was found between ADAMTS8 methylation status and lymph node metastasis." (PMID 27493958, 2016). "In addition, our results showed that a significant association was found between ADAMTS8 methylation status and lymph node metastasis." (PMID 27493958, 2016). "There was a significant correlation between ADAMTS8 expression and higher depth of tumor invasion, and the presence of lymph node metastasis." (PMID 37240178, 2023). "ADAMTS8 showed decreased mRNA expression in the primary tumors with T3 + T4 and lymph node metastasis." (PMID 27493958, 2016). "In our current study, we found that gastric cancer with lymph node metastases showed significantly lower expression of ADAMTS8." (PMID 27493958, 2016). "The results showed that the significant downregulation of ADAMTS8 mRNA expression was observed in gastric cancer cell lines and tissues, and its expression was related to invasive depth and lymph node metastasis." (PMID 27493958, 2016). "There was a significant correlation between the mRNA expression level of ADAMTS8 and invasive depth (P = 0.009) as well as lymph node metastasis (P < 0.001)." (PMID 27493958, 2016). "We also examined the relationship between ADAMTS8 methylation and the clinicopathologic features of the patients including age, gender, size, differentiation, depth of tumor invasion, and lymph node metastasis." (PMID 27493958, 2016). "With the utilization of the public web resource UALCAN, the expression levels of ADAMTS8 were found to be different between normal and tumor parts but not lymph node metastasis or stage-dependent." (PMID 35743687, 2022).
non-small cell lung carcinoma (6 papers, 2004 to 2021). A group of at least three distinct histological types of lung cancer, including non-small cell squamous cell carcinoma, adenocarcinoma, and large cell carcinoma. "Furthermore, the higher HJURP level could be associated with early-stage LC while lower ADAMTS8 level could be correlated with non-small cell lung cancer." (PMID 28410204, 2017). "Specifically, ADAMTS8 expression tended to be remarkably lower in non-small cell lung cancer group than small cell lung cancer group." (PMID 28410204, 2017). "It has been reported that ADAMTS8 expression was epigenetically silenced in brain cancer, non-small-cell lung cancer, and thyroid cancer." (PMID 27493958, 2016). "First clue of ADAMTS8 being a possible tumor suppressor gene surfaced upon gene expression analysis using microarray of primary non-small-cell lung carcinomas (NSCLC) versus normal lung tissue." (PMID 24213506, 2012). "Further studies clearly demonstrated that ADAMTS8 was epigenetically silenced in primary non-small-cell lung carcinomas (NSCLC)." (PMID 24213506, 2012). "There is evidence of modulation of expression of several of the ADAMTS genes in cancer, with significant downregulation (two-fold or lower) of ADAMTS-8 in non-small-cell lung cancer (NSCLC) and hypermethylation of the promoter region being a possible mechanism of gene silencing." (PMID 16570050, 2006). "The antiangiogenic factor METH-2 (ADAMTS-8) was identified in a previous dual-channel cDNA microarray analysis to be at least two-fold under-represented in 85% (28 out of 33) of primary non-small-cell lung carcinomas (NSCLCs)." (PMID 15328519, 2004).
lung adenocarcinoma (5 papers, 2016 to 2024). A carcinoma that arises from the lung and is characterized by the presence of malignant glandular epithelial cells. "These bioinformatics data suggest that low-expressed ADAMTS8 is associated with a more aggressive phenotype in lung adenocarcinoma." (PMID 35743687, 2022). "Patients with lower expression levels of ADAMTS8 survive for a shorter duration in lung adenocarcinoma." (PMID 35743687, 2022). "Among the top 10 genes with a high average ΔPCC in lung adenocarcinoma (LUAD), several genes such as CLDN18, ADAMTS8, PECAM1 and SFTPA1 have been known to be associated with LUAD in previous studies." (PMID 32854705, 2020). "Low-expressed ADAMTS8 potentiates more aggressive behaviors in lung adenocarcinoma." (PMID 35743687, 2022). "This study indicates that ADAMTS8 might be a treatment option for patients with lung adenocarcinoma who lack efficient targeted or immunotherapies." (PMID 35743687, 2022). "We found that RSPO3, ADAMTS8, DMBT1, DOCK8, STMN2, SPINK6 and TUSC3 were the co-genes of HOXA11-AS in lung adenocarcinoma whereas RSPO3, ADAMTS8, DMBT1, DOCK8, STMN2, SPINK6, TUSC3 and C8orf22 were the co-genes of HOXA11-AS in squamous cell carcinoma." (PMID 27980454, 2016). "In addition, RSPO3, ADAMTS8 and DOCK8 were related to overall survival and disease-free survival (all P < 0.05) of lung adenocarcinoma patients in TCGA." (PMID 27980454, 2016). "Furthermore, RSPO3, ADAMTS8 and DOCK8 were also related to the overall survival and disease-free survival of lung adenocarcinoma patients in the TCGA data." (PMID 27980454, 2016). "Additionally, ADAMTS8, DMBT1 and DOCK8 were down-regulated in adenocarcinoma and STMN2 and TUSC3 were up-regulated in lung adenocarcinoma (all P < 0.01)." (PMID 27980454, 2016). "Additionally, the original data from TCGA verified that ADAMTS8, DMBT1 and DOCK8 were downregulated in both lung adenocarcinoma and squamous cell carcinoma, whereas RSPO3 expression was upregulated in lung adenocarcinoma and downregulated in lung squamous cell carcinoma." (PMID 27980454, 2016). "ADAMTS8 might play a role in lung adenocarcinoma without targetable medication." (PMID 35743687, 2022).